EGFR (epidermal growth factor receptor)
Diseases named in the same sentence as EGFR in open-access papers (continued):
Sharing a sentence is not in itself a finding about the gene and the disease.
metastatic colorectal cancer (continued). "This trial established that the combination of the BRAF inhibitor encorafenib with EGFR monoclonal antibody cetuximab was superior to chemotherapy in pretreated patients with metastatic colorectal cancer bearing BRAF V600E mutations." (PMID 36079062, 2022). "Meanwhile, RAS mutations limit the effectiveness of anti-EGFR monoclonal antibodies in patients receiving chemotherapy for metastatic colorectal cancer." (PMID 35897925, 2022). "In light of these findings, the American Society of Clinical Oncology (ASCO) recommends testing both the EGFR and KRAS mutation status in patients with metastatic colorectal cancer who are candidates for anti-EGFR antibody therapy." (PMID 33801965, 2021). "MET overexpression/amplification has been associated with resistance to anti-epidermal growth factor receptor (EGFR) therapies in patients with KRAS wildtype metastatic colorectal cancer (mCRC)." (PMID 34504655, 2021). "KRAS mutations in metastatic colorectal cancer (mCRC) define a subset of tumors that have primary resistance to anti-EGFR-based therapy." (PMID 34660299, 2021). "The ESMO (2014), NICE (2020), and Australian (2017) guidelines recommend testing for BRAF mutation in metastatic colorectal cancer for prognostication and determination of response to anti-EGFR therapies." (PMID 34940086, 2021). "Resistant EGFR mutations were identified in patients with metastatic colorectal cancer under anti-EGFR treatment." (PMID 34830853, 2021). "For metastatic colorectal cancer, monoclonal antibody treatments have been used to block EGFR and cause its eventual ingestion." (PMID 32620824, 2020). "KRAS mutation is a confirmed predictive biomarker for anti-EGFR monoclonal antibody therapy response for metastatic colorectal cancer." (PMID 31952366, 2020). "KRAS and NRAS mutations are identified resistance mutations to anti-epidermal growth factor receptor monoclonal antibodies in patients with metastatic colorectal cancer." (PMID 30811471, 2019). "Recently, we found that TIMP‐1 plasma levels predicted benefit from EGFR‐inhibition therapy in KRAS‐mutated metastatic colorectal cancer patients." (PMID 31545548, 2019). "RAS mutations lead to primary resistance to EGFR blockade in metastatic colorectal cancer but are infrequent in HNSCC, suggesting that other mechanisms are implicated." (PMID 31640284, 2019). "Anti-EGFR monoclonal antibodies, including cetuximab and panitumumab, are used to treat patients with metastatic colorectal cancer, but are ineffective in tumors that have mutations in the RAS pathway (EGFR-RAS-RAF-MEK signaling cascade)." (PMID 30128304, 2018). "It is well known that activating mutations in the KRAS and NRAS genes are associated with poor response to anti-EGFR therapies in patients with metastatic colorectal cancer (mCRC)." (PMID 30344942, 2018). "We explored the concordance between the mutational status of RAS in tumor tissue and ctDNA in metastatic colorectal cancer (mCRC) patients to establish eligibility for anti-epidermal growth factor receptor (EGFR) therapy." (PMID 28368441, 2017). "Patients with BRAFV600E-mutated metastatic colorectal cancer (mCRC) have a poorer prognosis as well as resistance to anti-EGFR antibodies." (PMID 28972961, 2017). "Activating mutations in the KRAS gene, found in approximately 53% of metastatic colorectal cancer (mCRC) cases, can render epidermal growth factor receptor (EGFR) inhibitors ineffective." (PMID 28797274, 2017). "In conclusion, we found that EZH2 expression was associated with survival in patients with metastatic colorectal cancer who underwent surgical treatment and chemotherapy with anti-EGFR antibodies." (PMID 28147317, 2017). "An accurate blood‐based RAS mutation assay to determine eligibility of metastatic colorectal cancer (mCRC) patients for anti‐EGFR therapy would benefit clinical practice by better informing decisions to administer treatment independent of tissue availability." (PMID 28106345, 2017).
metastatic colorectal cancer (continued). "KRAS exon 2 mutations are predictive of resistance to epidermal growth factor receptor-directed monoclonal antibodies in patients with metastatic colorectal cancer." (PMID 26573425, 2016). "Metastatic colorectal cancer (CRC) patients with v‐Ki‐ras2 Kirsten rat sarcoma viral oncogene homolog (KRAS) mutations are resistant to monoclonal antibody that targets the epidermal growth factor receptor such as cetuximab." (PMID 26715098, 2016). "In metastatic colorectal cancer (mCRC) resistance mechanisms are by far better understood and involve mutations in EGFR downstream signaling molecules such as RAS." (PMID 27119512, 2016). "Targeted therapy against the epidermal growth factor receptor (EGFR) represents a well-accepted and effective treatment strategy in metastatic colorectal cancer associated with an increased response rate and prolonged patient survival." (PMID 27064574, 2016). "KRAS mutation testing is mandatory in the management of metastatic colorectal cancer prior to treatment with anti-EGFR antibodies as patients whose tumors express mutant KRAS do not benefit from these agents." (PMID 27485514, 2016). "Recent studies showed that other activating mutations in KRAS (exons 3 and 4) or NRAS (exons 2, 3 and 4), in addition to KRAS mutation in exon 2 are also associated with poor prognosis or resistance to anti-EGFR antibody in metastatic colorectal cancer." (PMID 25954997, 2015). "This study supports the observation that detection of K-ras mutation is a useful predictor for anti-EGFR-TK treatment in metastatic colorectal cancer." (PMID 25950441, 2015). "KRAS mutation assays are important companion diagnostic tests to guide anti-EGFR antibody treatment of metastatic colorectal cancer." (PMID 25568935, 2015). "This study detected K-ras mutations to predict the efficacy of EGFR-TK inhibitor cetuximab treatment on Chinese patients with metastatic colorectal cancer (mCRC)." (PMID 25950441, 2015). "KRAS is an oncogene, located on chromosome 6, which encodes a protein with an important physiological and pathogenic role in metastatic colorectal cancer (a key protein in EGFR signalling cascade)." (PMID 26557880, 2015). "KRAS mutation assays are important companion diagnostic tests to guide the use of anti-EGFR antibody treatment of metastatic colorectal cancer." (PMID 25568935, 2015). "Epidermal growth factor receptor (EGFR) inhibitors are approved for treating metastatic colorectal cancer (CRC); KRAS mutation testing is recommended prior to treatment." (PMID 24788807, 2014). "K-ras is now also widely accepted as a predictor of poor response to antiepidermal growth factor receptor (EGFR) monoclonal antibodies in metastatic colorectal cancer and testing for K-ras mutation has been incorporated into treatment." (PMID 25301978, 2014). "Several studies have examined the predictive value of KRAS mutation in codon 61 and/or 146 in metastatic colorectal cancer (CRC) treated with anti-EGFR therapy." (PMID 25361007, 2014). "Several studies have examined the predictive value of KRAS mutation in codon 61 and/or 146 in metastatic colorectal cancer treated with anti-EGFR therapy (cetuximab or panitumumab)." (PMID 24885062, 2014). "Then we analyzed the correlation between the abundance of KRAS mutations and efficacy of EGFR antibody therapy in another 35 metastatic colorectal cancer patients." (PMID 23874486, 2013). "KRAS is an EGFR effector in the RAS/RAF/ERK cascade that is mutated in about 40% of metastatic colorectal cancer (mCRC)." (PMID 23548132, 2013). "In particular, KRAS mutations are strong predictors for clinical outcomes of EGFR-targeted treatments such as cetuximab and panitumumab in metastatic colorectal cancer (mCRC)." (PMID 23671647, 2013).
metastatic colorectal cancer (continued). "Cetuximab and panitumumab are effective epidermal growth factor receptor (EGFR) targeted agents for metastatic colorectal cancer (mCRC), but patients whose tumors have KRAS mutations except G13D are generally believed to not benefit from these agents." (PMID 23671647, 2013). "BRAF mutation has been investigated as a prognostic factor in metastatic colorectal cancer (mCRC) undergoing anti-EGFR monoclonal antibodies (moAbs), but current results are still inconclusive." (PMID 23776587, 2013). "Mutations in the KRAS gene are associated with poor response to epidermal growth factor receptor inhibitors used in the treatment of metastatic colorectal cancer." (PMID 22534075, 2012). "The predictive value of KRAS mutation in metastatic colorectal cancer patients treated with anti-EGFR monoclonal antibodies, cetuximab or panitumumab, has recently been suggested." (PMID 20977739, 2010). "PIK3CA mutations have been reported to be associated with resistance to EGFR-targeted monoclonal antibodies in patients with metastatic colorectal cancers (mCRC)." (PMID 19636423, 2009). "Several studies have reported positive associations between EGFR gene amplification and metastatic colorectal cancer response to EGFR-directed antibodies." (PMID 19636423, 2009). "KRAS mutations occur in 35–45% of metastatic colorectal cancers (mCRC) and preclude responsiveness to EGFR-targeted therapy with cetuximab or panitumumab." (PMID 19806185, 2009). "KRAS codons 12 and 13 mutations predict resistance to anti-EGFR monoclonal antibodies (moAbs) in metastatic colorectal cancer." (PMID 19603018, 2009). "Anti-EGFR targeted therapy is a potent strategy in the treatment of metastatic colorectal cancer (mCRC) but activating mutations in the KRAS gene are associated with poor response to this treatment." (PMID 20300583, 2009). "Additionally, a study identified ZNF217 with increased mutation frequency after anti‐EGFR therapy in metastatic colorectal cancer patients, while a mutation in ZNF217 and low TMB in this study were found to be significantly associated with treatment response." (PMID 39712455, 2025). "Additionally, resistance to cetuximab and panitumumab in metastatic colorectal cancer (mCRC) has been associated with the increased expression of EGFR ligands, structural alterations in EGFR, and autophagy." (PMID 40725201, 2025). "Epidermal growth factor receptor (EGFR) inhibition is crucial in treating RAS wild-type metastatic colorectal cancer, yet current testing methods may miss rare RAS variants affecting treatment efficacy." (PMID 39727997, 2024). "HER2 overexpression/amplification in patients with RAS wild-type (WT) metastatic colorectal cancer (mCRC) may be associated with resistance to standard-of-care anti-EGFR therapies." (PMID 37463037, 2023). "Recent studies have shown that a number of EGFR ECD mutations may be acquired in patients with metastatic colorectal cancer (mCRC) after cetuximab and/or panitumumab treatment." (PMID 35907884, 2022). "Monoclonal antibodies, such as cetuximab and panitumumab, and tyrosine kinase inhibitors (TKIs) have been developed and approved for the treatment of EGFR-mutated non-small cell lung cancer (NSCLC), EGFR-expressing metastatic colorectal cancer (mCRC) with KRAS wild type, and head and neck cancers." (PMID 33918836, 2021). "Anti-EGFR resistance in metastatic colorectal cancer (MCRC) may be linked to changes in the transcription factor c-MYC (MYC)." (PMID 34836311, 2021). "Drugs targeting the epidermal growth factor receptor (EGFR), such as cetuximab and panitumumab, have been prescribed for metastatic colorectal cancer (CRC), but patients harboring KRAS mutations are insensitive to them and do not have an alternative drug to overcome the problem." (PMID 30459318, 2018).
metastatic colorectal cancer (continued). "In 2009, the US Food and Drug Administration (FDA) approved EGFR-targeted monoclonal antibody therapy with cetuximab and panitumumab in patients with metastatic colorectal cancer (mCRC) along with analysis of KRAS mutation status, which is a predictive biological marker of resistance." (PMID 28797274, 2017). "Hence, an alternative method for detecting KRAS gene mutations in these metastatic colorectal cancer patients treated with anti-EGFR is needed." (PMID 24884535, 2014). "The issue of whether patients diagnosed with metastatic colorectal cancer who harbor KRAS codon 13 mutations could benefit from the addition of anti-epidermal growth factor receptor therapy remains under debate." (PMID 23437064, 2013). "As far as we know, we firstly showed that low abundance of KRAS mutation (<30%) might also benefit from anti-EGFR treatment in metastatic colorectal cancer patients." (PMID 23874486, 2013). "Conversely, another study of 173 patients with KRas wild-type metastatic colorectal cancer treated with a cetuximab-based regimen found that EGFR amplification/increased EGFR copy number, present in 17.7% of patients, was associated with response to anti-EGFR therapy." (PMID 21403829, 2011). "Our aim was to investigate the prognostic and predictive value of the oncogenic MAPKK-like protein T-cell-originated protein kinase (TOPK) stratified by KRAS and BRAF mutations in patients with sporadic, hereditary and metastatic colorectal cancer (CRC) treated with anti-EGFR therapy." (PMID 19935791, 2010). "Randomised trials in metastatic colorectal cancer have demonstrated that use of monoclonal antibodies directed against EGFR (HER-1), namely cetuximab and panitumumab, is associated with favourable outcomes in patients expressing the wild-type form of K-ras proto-oncogene." (PMID 21063399, 2010). "The second and major part of our study was to investigate whether therapy-related resistance due to acquired second KRAS/BRAF mutations also occurs in metastatic colorectal cancer after anti-EGFR therapy." (PMID 20300583, 2009). "Preliminary evidence also suggests that tracking the emergence and decline in rat sarcoma virus oncogene (RAS) mutated clones driving resistance in metastatic colorectal cancer patients treated with anti-EGFR antibodies may guide the timing of anti-EGFR rechallenge." (PMID 33440749, 2021). "Furthermore, KRAS mutations are also used as major prognostic biomarkers for therapies that target the EGFR in patients with metastatic colorectal cancer, as cancer bearing KRAS mutations are reportedly unresponsive to anti- EGFR monoclonal antibodies such as cetuximab and panitumumab." (PMID 30504843, 2018). "However, it remains unknown whether EGFR pathway mutations affect the efficacy of bevacizumab (Bmab) in metastatic colorectal cancer (mCRC)." (PMID 28068936, 2017). "Considering that KRAS codon 61 and 146 mutations may also confer resistance to EGFR inhibitors, patients who have metastatic colorectal cancer with KRAS mutation in codon 61 or 146 could receive more tailored management through clinical testing of these additional KRAS codons." (PMID 24885062, 2014). "Similarly, the anti-EGFR antibody cetuximab was associated with significant worsening of outcome when added to standard therapy in the treatment of KRAS-mutant metastatic colorectal cancer, while it may improve outcome in KRAS-wild-type patients." (PMID 23587187, 2013). "Furthermore, De Roock and colleagues recently reported that chemotherapy-refractory metastatic colorectal cancers harboring a G13D KRAS mutation were more sensitive to treatment with the epidermal growth factor receptor (EGFR) inhibitor cetuximab compared to tumors with other KRAS mutations." (PMID 22382702, 2012).
metastatic colorectal cancer (continued). "Recent clinical data convincingly associates response to anti-EGFR therapies with K-Ras mutation status in patients with metastatic colorectal cancer where, logically, response is preferentially observed in K-Ras wt tumours which retain the ability to respond to EGFR blockade." (PMID 20147967, 2010). "This study evaluated the prognostic significance of anti-EGFR-related skin toxicity in patients with RAS wild-type metastatic colorectal cancer (mCRC) receiving palliative chemotherapy." (PMID 42122963, 2026). "Epidermal growth factor receptor (EGFR) blockade combined with cytotoxic chemotherapy has substantially improved outcomes in unresectable metastatic colorectal cancer (mCRC), particularly in patients with left-sided RAS wild-type disease [...]." (PMID 42279271, 2026). "The combination of a BRAF inhibitor (BRAFi) together with an anti-EGFR inhibitor (EGFRi) represents a standard of care approach in BRAFV600E metastatic colorectal cancer (mCRC) patients." (PMID 41882736, 2026). "In this study, patients with resectable isolated liver metastatic colorectal cancer were assessed, and the addition of anti-EGFR therapy was found to have a detrimental effect." (PMID 40428735, 2025). "Skin lesions are prevalent in patients with metastatic colorectal cancer (mCRC) receiving epidermal growth factor receptor (EGFR) inhibitors, such as panitumumab and cetuximab, often necessitating long-term management." (PMID 40130130, 2025). "First-line treatment for patients with microsatellite stable, RAS wild-type, and left-sided metastatic colorectal cancer consists of anti-EGFR (epidermal growth factor receptor) plus chemotherapy." (PMID 41305005, 2025). "Systemic treatment for metastatic colorectal cancer relies on cytotoxic chemotherapy with the addition of monoclonal antibodies targeting angiogenesis or the tyrosine kinase receptor EGFR for patients with a wild-type KRAS oncogene." (PMID 40004631, 2025). "As a result, anti-EGFR therapies such as cetuximab and panitumumab become ineffective, leading to primary resistance in metastatic colorectal cancer patients." (PMID 40282985, 2025). "Circ-EGFR was identified as a novel predictive biomarker for cetuximab efficacy in KRAS wild-type metastatic colorectal cancer, which was successfully translated into a non-invasive liquid biopsy assay for predicting responses to anti-EGFR therapy." (PMID 41214390, 2025). "Primary mechanisms of intrinsic resistance to anti-EGFR therapy in metastatic colorectal cancer (mCRC)." (PMID 40940901, 2025). "The introduction of monoclonal antibodies targeting the epidermal growth factor receptor (EGFR) has represented a milestone in the management of metastatic colorectal cancer (mCRC)." (PMID 41214389, 2025). "Epidermal growth factor receptor (EGFR) inhibitors remain a cornerstone in the treatment of metastatic colorectal cancer with RAS and BRAF wild-type cancer." (PMID 40940901, 2025). "Cetuximab is a chimeric EGFR‐targeting antibody used to treat patients with EGFR‐overexpressing cancers including metastatic colorectal cancer." (PMID 40395357, 2025). "We investigated genetic mutations in 142 samples from primary tumours of 39 KRAS wild‐type metastatic colorectal cancer (CRC) patients receiving anti‐EGFR therapy." (PMID 40302146, 2025). "In metastatic colorectal cancer (mCRC), KRAS and BRAF mutations are well-known markers of resistance and poor prognosis in patients receiving anti-epidermal growth factor receptor (EGFR) monoclonal antibodies." (PMID 40279317, 2025). "The introduction of cetuximab and PAN, which specifically target the EGFR, improved survival outcomes for 10–20% of patients with metastatic colorectal cancer (mCRC)." (PMID 40002260, 2025). "Maintenance with anti-EGFR in metastatic colorectal cancer (mCRC) with wild type Ras was studied in many trials with promising results." (PMID 39945465, 2025).